OGT (O-linked N-acetylglucosamine (GlcNAc) transferase)
Diseases named in the same sentence as OGT in open-access papers (continued):
Sharing a sentence is not in itself a finding about the gene and the disease.
tumor (continued). "The results showed that tumor size and weight were lower in mice injected with OGT R348K mutant cells than in those injected with OGT WT and the R348F mutant." (PMID 39715739, 2024). "OGT promotes tumor proliferation primarily through its involvement in regulating protein post-translational modifications (PTMs)." (PMID 39285476, 2024). "IHC staining revealed that mouse OGT protein was markedly higher in tumor tissues than in adjacent tissues, which was consistent with the expression pattern in human samples." (PMID 38168435, 2024). "O-GlcNAcylation catalyzed by O-GlcNAc transferase (OGT) plays an important role in the regulation of tumor glycolysis." (PMID 39715739, 2024). "This underscores the need for personalised treatment research to determine the sensitivity of different tumour types to OGT inhibitors." (PMID 39358921, 2024). "Here, we show that OGT is essential for tumor growth in immunocompetent mice by repressing the cyclic GMP-AMP synthase (cGAS)-dependent DNA sensing pathway." (PMID 39365288, 2024). "Here, we show that OGT is essential for tumor growth in immunocompetent hosts by repressing the cyclic GMP-AMP synthase (cGAS)-dependent DNA sensing pathway." (PMID 38168435, 2024). "Intestinal OGT protein was markedly increased in Apcmin mouse tumor tissues compared to adjacent or normal tissues." (PMID 38168435, 2024). "As we expected, decreased tumor growth and prolong mice survival phenotype disappeared both in OGT rescued cells and in OGT/cGAS or OGT/STING double knockout tumors." (PMID 38168435, 2024). "We identify the USP8 is a β-catenin DUB that stabilizes OGT and promotes tumor growth, invasion, though its deubiquitylation activity." (PMID 38973004, 2024). "OGT is the only glycosyltransferase catalyzing O-GlcNAcylation, and thus plays an important role in the regulation of tumor cell metabolism and cell proliferation." (PMID 39715739, 2024). "OGT has been shown to promote tumor development, and the results of this study confirmed that OGT is an oncogenic factor in NSCLC." (PMID 39715739, 2024). "Overexpression of OGT also rescued the decreased tumor xenografts growth of LNCaP-AI cells induced by shKIF1A." (PMID 39505875, 2024). "The expression of FASN, GFPT1, OGT and O-GlcNAc is much higher in tumor tissues as compared to normal mucosa." (PMID 38732103, 2024). "The lack of nutrients triggers the metabolic reprogramming of endothelial cells by tumor-derived extracellular vesicles, leading to OGT-catalyzed O-GlcNAcylation of SerRS." (PMID 38255739, 2024). "Further research is required to elucidate the interaction between OGT and autophagy-related molecules and to characterize its role in tumor progression." (PMID 39285476, 2024). "Given OGT’s role in promoting tumor progression, studies have shown that it inhibits tumor cell apoptosis." (PMID 39285476, 2024). "Whole transcriptome analysis after OGT knockdown revealed downregulation of several genes known to be crucial for cell proliferation, tumor invasion, and metastasis." (PMID 37689115, 2023). "Aberrant O-GlcNAcylation and the altered protein expression of OGT and OGA are associated with poor prognoses and tumor grades in some cancer types." (PMID 37835434, 2023). "Here in this review, we will present and discuss the latest findings that shed light on the involvement of OGT and O-GlcNAc in tumor development." (PMID 37838167, 2023). "In sum, these results demonstrate that glucose flux regulated mitochondrial motility in NSCLC tumour cells through the hexosamine pathway and OGT." (PMID 36922590, 2023). "Collectively, these reports not only support the notion that O-GlcNAcylation as a PTM links metabolic changes to inflammation and tumor progression but also affirm that OGT is important for the regulation of NF-κB signaling." (PMID 37835439, 2023).
tumor (continued). "Aberrant O-GlcNAcylation is related to the tumorigenesis of several tumor types, and targeting O-GlcNAc transferase (OGT) is a possible therapeutic target for some tumor types." (PMID 37835434, 2023). "Expression of OGT and O-GlcNAc levels are highly elevated in metastasized thyroid tumors when compared to primary tumor." (PMID 37838167, 2023). "We previously identified a critical role of OGT and O-GlcNAc in promoting CSCs phenotype and tumor initiation, potentially via upregulating KLF8 expression." (PMID 37152043, 2023). "We showed that OGT levels were higher in TNBC cell lines compared to non-tumor breast cells, matching patient data." (PMID 37231419, 2023). "CEMIP- and OGT-induced nuclear accumulation of β-catenin can transactivate genes in metabolic reprogramming and promote tumor growth." (PMID 36291918, 2022). "The results showed that higher OGT and OGA levels were associated with higher histological grades and depth of tumor invasion into the myometrium." (PMID 36104770, 2022). "We subsequently verified the suppressive effects of OGT-KD monotherapy on cell migration/invasion in vitro and xenograft tumor growth in vivo in chemoresistant UCB cells." (PMID 35625898, 2022). "First, we validated the tumor-specific upregulation of the transcriptional and translational levels of OGT (tumor-specific upregulation of OGT/O-GlcNAc) in various UCB cell lines." (PMID 35625898, 2022). "For example, increased expression of OGT was found to be related to the histological grade of the tumor in breast cancer, and blocking O-GlcNAcylation resulted in reduced vascular endothelial factor expression and impaired angiogenesis in prostate cancer." (PMID 35795059, 2022). "The level of OGT and protein O-GlcNAcylation was significantly higher in tumor tissues than that in adjacent tissues." (PMID 34354953, 2021). "Gene expression analysis of urine sediments from bladder cancer (BC) patients revealed the relationship between tumor grades and OGT/OGA expression." (PMID 33535386, 2021). "Accordingly, several solid and non-solid cancers exhibit increased O-GlcNAcylation and elevated levels of OGT, which are positively related to higher tumor aggressiveness and poor prognosis." (PMID 34298689, 2021). "Cell lines of breast, colorectal, prostate, and hepatocellular carcinoma treated with investigational OGT inhibitors have shown a significant decrease in tumor growth." (PMID 34771527, 2021). "Blocking OGT increases sensitivity to oxidative stress and DNA damage, leading to apoptosis or senescence and preventing tumor progression." (PMID 34868034, 2021). "Recent studies report that the level of O-GlcNAc and OGT increases in tumor tissues as compared to adjacent healthy tissues." (PMID 33251387, 2020). "Knocking down OGT inhibited tumour growth, decreased cell cycle progression, increased expression of the cell cycle inhibitor p27Kip1, and decreased invasiveness." (PMID 31560077, 2020). "OGT inhibition has been reported to inhibit proliferation and tumor drug resistance by directly affecting the NF-κB pathway in HCC." (PMID 33121131, 2020). "Taken together, the changes in OGT/O-GlcNAcylation level directly affect tumor occurrence and progression." (PMID 33194731, 2020). "Tumor cells can elevate the total O-GlcNAc levels by increasing OGT or decreasing OGA, but for some tumors, O-GlcNAc deregulation is also known." (PMID 31466420, 2019). "The Ki-67 levels was lower in tumor tissues from the OGT knockdown group than in the control group, indicating a tumor-suppressing potential." (PMID 30453909, 2018). "Consistently, the immunohistochemical (IHC) analysis illustrated an obvious augmentation of O-GlcNAcylation and expression of OGT in clinical tumor samples of bladder than in adjacent normal tissues." (PMID 30453909, 2018). "The tumor size of OGT knockdown cells was significantly reduced by bortezomib treatment on day 6, whereas that of control cells was not affected." (PMID 29941490, 2018).
tumor (continued). "Since O-GlcNAcylation is sensitive to metabolic state and is involved in tumor growth in vitro, we determined the expression of OGT and OGA mRNA." (PMID 30217067, 2018). "It is contrary to the general view that by reducing O-GlcNAcylation (via a decrease in OGT) tumor growth is inhibited." (PMID 30217067, 2018). "Univariate analysis showed that tumor necrosis, tumor differentiation, histological subtype, and OGT expression influenced RFS in cohort A patients." (PMID 30123425, 2018). "The activity and expression of O-GlcNAc transferase (OGT) that catalyzes O-GlcNAcylation processes in a nutrient-dependent manner are also increased in tumor cells." (PMID 26835421, 2016). "Both enzymes indirectly use the same substrate, glucose, and glutamine for OGT, the fluxes of which are accelerated in tumor cells." (PMID 26835421, 2016). "Most importantly, in nude mice, tumor volume from HeLa cells treated with OGT–specific shRNA was significantly reduced compared to those with non-targeting shRNA." (PMID 27331873, 2016). "We observed that c-Myc activation forms a positive feedback loop with OGT, which plays a critical role in uncontrolled proliferation of tumor cells." (PMID 27703839, 2016). "In this perspective, we collected data linking FAS and OGT and, in so doing, pave the way for the exploration of the intricate functions of these two actors that play a central role in tumor growth." (PMID 26835421, 2016). "Cells in the context of OGT depletion decreased tumor volume (P < 0.05) and tumor weight (P < 0.05) compared to cells with non-targeting shRNA." (PMID 27331873, 2016). "Downregulation of OGT in tumor cells leads to increased degradation of the oncogenic transcription factor Forkhead transcription factor (FoxM1) protein, a direct regulator of VEGFR-2 and FoxF1 expression in EC." (PMID 25149532, 2014). "Immunochemistry analysis of patient samples showed that O-GlcNAc and OGT has the same alterations found in other tissues, with increased protein levels in tumor tissues when compared with adjacent healthy tissue, and that OGA levels appear to be unaltered." (PMID 24918087, 2014). "To confirm effective delivery of miR-7 into the tumor tissue we performed IHC staining of OGT, one of the target genes of miR-7." (PMID 25149532, 2014). "Measuring normal pancreas and tumor cell lines showed that OGT protein levels in tumors were higher than in normal cell lines and that OGA levels were decreased." (PMID 24918087, 2014). "Lynch and colleagues showed that O-GlcNAc and OGT levels are higher and OGA/OGT ratios are lower in tumor cells than in normal cells lines." (PMID 24918087, 2014). "To further investigate the role of OGT in regulating sensitivity to inhibitors of the PI3K pathway, we next analyzed the effects that the loss of OGT expression had on tumor cell line sensitivity to the dual PI3K/mTOR inhibitor, NVP-BEZ235." (PMID 23029544, 2012). "A self-reinforcing circuit marked by OGT-mediated O-GlcNAcylation and tumor hypersialylation through ST3GALs drives proteome-wide remodeling and immune evasion, enhancing PD-L1 stability and promoting Siglec-mediated polarization of tumor-associated macrophages (TAMs)." (PMID 41228299, 2025). "In MASLD‐HCC, highly expressed OGT promotes tumor progression through dual signaling pathways." (PMID 41394960, 2025). "Similarly, RNAi inhibition of OGT in breast cancer cells led to the inhibition of tumour growth both in vitro and in vivo, decreased cell cycle progression and the upregulation of cell cycle inhibitor p27 (Kip1)." (PMID 39474868, 2024). "Knockdown of OGT can inhibit tumor cell proliferation and induce apoptosis." (PMID 38983924, 2024). "Furthermore, OGT inhibitors are increasingly recognised as immune modulation targets, capable of enhancing immune responses within the tumour microenvironment, which offers new strategies for immunotherapy." (PMID 39358921, 2024).
tumor (continued). "Recent reports indicate that OGT inhibitors exert anti‐tumour effects through various mechanisms." (PMID 39358921, 2024). "Additionally, HSD enhances tumour growth in HipkOE tumours by allowing excess sugar to couple with the HIPK protein through OGT, further promoting tumour progression." (PMID 39682725, 2024). "Recent studies have identified OGT as a key regulator of tumor invasion and metastasis." (PMID 39285476, 2024). "Compared to normal bone tissues, tumor tissues had higher OGT mRNA expression levels." (PMID 38217543, 2024). "Although OGT can be ubiquitinated, the expression of OGT increased in most tumor cells." (PMID 39715739, 2024). "Furthermore, shHK3 suppressed both basal levels and OGT-elevated PD-L1 and O-GlcNAcylation, signifying that the high basal level of tumor HK3, along with OGT-induced HK3, both played a role in PD-L1 expression following OGT stimulation." (PMID 39179546, 2024). "OGT regulates matrix metalloproteinase levels, thereby affecting tumor metastasis." (PMID 39285476, 2024). "OGT-related pro-tumor mechanisms were also investigated using KEGG pathway analysis." (PMID 38217543, 2024). "OGT and O-GlcNAcylation can regulate many hallmarks of tumor progression." (PMID 37152043, 2023). "In our model, upregulated tumor OGT levels could be a product of feed-forward regulation in three steps." (PMID 37231419, 2023). "We measured the maximal OCR in tumour cells following inhibition of glucose flux, the hexosamine pathway and OGT and these all induced a significant increase in basal and maximum OCR, as well as the complex I and II MRC in RH2, and to a lesser extent in H1975 cells." (PMID 36922590, 2023). "In all tumor types, OGT was overexpressed at the protein level, matching prior reports." (PMID 37231419, 2023). "Moreover, pathway analysis on the list of DEGs in OGT knockdown cells showed various cell division and cell cycle pathways, regulation of epithelial to mesenchymal transition, and tumor microenvironment pathways enriched among others." (PMID 37689115, 2023). "We employed a model for studying resistance to GEM or PTX in UCB using two initial cell lines (UMUC-3 and T24) to provide novel insights into the molecular mechanisms involved in enhanced chemoresistance and tumor aggression in UCB by elevated expression of OGT and O-GlcNAc." (PMID 35625898, 2022). "Moreover, OGT is associated with TETs to control O-GlcNAcylation of histone H2B for activation of gene transcription, while OGT is coordinated with EZH2 to modulate H3K27me3 for silence of tumor suppressor genes." (PMID 35935878, 2022). "In tumor cells, O-GlcNAc proteins could promote vimentin expression and cell migration, while OGT catalyzes O-GlcNAc proteins to exert its effect." (PMID 36544170, 2022). "Notably, various groups have shown the contribution of upregulated OGT and hyper-O-GlcNAcylation to unfavorable pathology and tumor aggressiveness in UCB." (PMID 35625898, 2022). "Furthermore, they showed that OGT has tumor suppressive activity in myeloid malignancies, especially in the presence of ASXL1 mutations." (PMID 36104770, 2022). "For example, the role of OGT as a tumor promoter or suppressor in CLL could be addressed in more detail by B cell lineage specific deletion of OGT in TCL1-transgenic mice, considered an excellent model of aggressive IGHV unmutated CLL." (PMID 34868034, 2021).
tumor (continued). "For example, OGT and O-GlcNAcylation may have tumor suppressor activity early in the course of MDS and AML when ASXL1 is intact but acquire tumor promoting activity when ASXL1 is inactivated by mutation." (PMID 34868034, 2021). "Notably, the overexpression of O-GlcNAc transferase (OGT), an enzyme involved in tumor-initiating cell-mediated rewiring of energy metabolism, increases CSC populations and mammosphere formation in vitro and in vivo." (PMID 33299638, 2020). "Importantly, in vivo xenograft experiments also demonstrated that the OGT knockdown group has less tumor volume than the control group." (PMID 32863962, 2020). "In addition, it has been shown that OGT overexpression promotes tumor initiation in mouse models of breast cancer." (PMID 33046784, 2020). "Further, downregulating OGT inhibits tumor formation and growth." (PMID 30453909, 2018). "The mutations in this tumor included 3 predicted high impact mutations in MTOR a regulator of stress response, OGT a glycosyltransferase that modifies a broad range of targets including H2B, AKT1, EZH2, PFKL, KMT2E/MLL5, MAPT/TAU and HCFC1, and FAM129B a negative regulator of apoptosis." (PMID 28415633, 2017). "We also found that the growth rate of xenografts with OGT knocked down was much slower than that of the control xenografts, and reduced tumour growth could also be reversed by overexpression of YAP." (PMID 28474680, 2017). "Interestingly, the inhibition of OGT in breast cancer cells induces a reduction in cell proliferation, invasion, and migration, and a decrease in tumor growth." (PMID 26835421, 2016). "Further, to test whether OGT is required for tumor growth in vivo, HeLa cells stably expressing either control or OGT shRNA were injected subcutaneously into the right flank of nude (Nu/Nu) mice." (PMID 27331873, 2016). "Importantly, OGT is required for tumor growth and colony formation in vitro, and invasion and metastasis in vivo." (PMID 27331873, 2016). "Tumor progressions were accompanied by increased levels of OGT mRNA and decreasing OGA mRNA." (PMID 24918087, 2014). "Furthermore, not only tumor vessel density was reduced, expression of the nuclear proliferation marker Ki-67 and expression of the newly identified miR-7 target gene OGT were also affected by miR-7 treatment in vivo." (PMID 25149532, 2014). "We next probed for alterations in cellular signaling pathways that may be driving the increased sensitivity observed upon loss of OGT expression in the MDA-MB-231 and OVCAR-4 tumor cell lines." (PMID 23029544, 2012). "However, we did observe decreased levels of total Cyclin D1 in OVCAR-4 tumor cells treated with OGT siRNA and 4 μM GDC-0941, relative to GDC-0941- or OGT siRNA-alone treated cells." (PMID 23029544, 2012). "The work presented presents multiple lines of evidence to support the hypothesis that OGT and O-GlcNAc glycosylation may modulate tumor cell line response to PI3K inhibitors." (PMID 23029544, 2012). "Additionally, tumour heterogeneity complicates targeted therapy against OGT." (PMID 39358921, 2024). "Therefore, identifying the signaling networks that regulate CSC properties via OGT could contribute to more effective tumor treatments." (PMID 39285476, 2024). "In future studies, it will be interesting to determine whether the content of OGT and O-GlcNAc in tumor tissues, urine, or blood could represent useful predictive biomarkers of disease progression and clinical outcomes in advanced UCB patients treated with chemotherapeutic agents." (PMID 35625898, 2022). "Increasing O-GlcNAc and OGT may be also involved in tumor invasion and metastasis." (PMID 31466420, 2019).